INS (insulin)
Diseases named in the same sentence as INS in open-access papers (continued):
Sharing a sentence is not in itself a finding about the gene and the disease.
type 2 diabetes (continued). "RT has a strong clinical background for the prevention and management of type 2 diabetes, improving visceral fat quantity, HbA1c blood levels, glucose transporter type 4 distribution, and insulin sensitivity." (PMID 34408664, 2021). "The GLP-1R, upon activation, exerts several metabolic effects including the release of insulin and suppression of appetite, and has, accordingly, become an important target for the treatment for type 2 diabetes (T2D)." (PMID 34040588, 2021). "In type 2 diabetes, however, initially β‐cells are functional and can still secrete insulin upon high blood glucose concentrations." (PMID 34319011, 2021). "Activation of PPAR-γ has been reported to improve blood glucose control and systemic insulin sensitivity in patients with type 2 diabetes." (PMID 34194325, 2021). "The aim of this study was to investigate if MR blockade would have a beneficial effect on insulin sensitivity in individuals with type 2 diabetes." (PMID 34350730, 2021). "In type 2 diabetes, the most common form of this disease (80–90% of all patients), beta cell mass has been reported to be decreased by approximately 30%, with specific insulin secretion functional impairments possibly playing the key role in most cases." (PMID 34440644, 2021). "The effect of type-2 diabetes on cognitive status can be answered by first proving that insulin and insulin receptors do exist in the brain and follow a certain pattern to serve a certain function in promoting cognitive status." (PMID 34877187, 2021). "The first phase of insulin secretion plays an important role in postprandial glucose homeostasis, and it is often lost or reduced in early stages of type-2 diabetes (T2D; see later sections)." (PMID 33146746, 2021). "Insulin is the mainstay of treatment for type 1 diabetes, but for type 2 diabetes, both hypoglycemic medication and insulin are used." (PMID 34830886, 2021). "During the low dose of infused insulin, a lower achieved plasma insulin concentration was present in the healthy controls compared to the individuals with type 2 diabetes following intervention." (PMID 34350730, 2021). "Analysis results revealed that LWDHW is related to the delay of insulin use in type 2 diabetic patients with dose-dependent effects." (PMID 34457016, 2021). "In type 2 diabetics, it was found that intranasal insulin did not only affect fasting and postprandial blood glucose levels but did so in a way that simplified dosing too." (PMID 34540446, 2021). "Type 2 diabetes is more common and occurs when the body becomes resistant to insulin or cannot produce enough insulin." (PMID 34367309, 2021). "Type 2 diabetes mellitus (T2DM) is a metabolic disease characterized by insulin secretion reduction or insulin resistance that results in hyperglycemia." (PMID 34684055, 2021). "This notwithstanding, we demonstrate here for the first time that type 2 diabetes in humans is accompanied by both insulin and IGF-1 resistance at the level of the endothelium, providing a conceptual framework for the present study." (PMID 34420367, 2021). "The utility of PEGylation technology in the treatment of type 2 diabetes was previously explored in the PEGylation of basal insulin." (PMID 33687487, 2021). "In this study, we quantified hypoglycaemia events in a sample of patients with type 2 diabetes who recently initiated treatment with basal insulin or who initiated treatment within a year prior to study entry, who were followed up during a 24‐week period." (PMID 33532606, 2021). "Type 2 diabetes mellitus (T2DM) is a heterogeneous metabolic disorder characterized by reduced insulin sensitivity and relative insulin deficiency, which increases the risk for cognitive decline and dementia, such as Alzheimer’s disease (AD) and vascular dementia." (PMID 33613213, 2021). "In the case of insulin-induced severe hypoglycemia, the brain glucose level rapidly descends, leading to cognitive dysfunction, namely seizure and coma." (PMID 35095392, 2021).
type 2 diabetes (continued). "Throughout the seven waves, patients with type 2 diabetes treated solely with OGLDs had the lowest proportion of microalbuminuria/proteinuria and those treated with insulin alone had the highest." (PMID 33594476, 2021). "Our study has provided information that the initial blood glucose can give an idea about the optimal duration of intensive insulin therapy in patients with newly diagnosed Type-2 diabetes who are metabolically glucotoxic." (PMID 34912428, 2021). "The number of patients with type 2 diabetes who were receiving insulin pump therapy was too small to allow a multivariable analysis that included pump use." (PMID 34570208, 2021). "Retinoids and retinoid-related proteins are associated with signaling molecules linking obesity with the development of type 2 diabetes and in the pancreatic β-cell biology/insulin secretion." (PMID 34367469, 2021). "In healthy patients with both type 1 and type 2 diabetes, insulin infusion (with dextrose to maintain euglycemia) leads to decreased reactive oxygen species, systemic cytokine gene expression and serum CRP levels." (PMID 33992101, 2021). "Although plasma insulin levels were similar between participants with obesity and type 2 diabetes, the levels observed in these groups were significantly higher compared with both lean and endurance-trained individuals (both p < 0.01)." (PMID 33258025, 2021). "SNPs around the exon region of the GLP1R gene were genotyped in a small sample of people with poorly controlled type 2 diabetes, who received exenatide for 3 days (5 μg twice daily) and were also treated with a continuous subcutaneous insulin infusion." (PMID 33594477, 2021). "The efficacy and safety of BBR with insulin in improving DR were elaborated in experimental in type I and type II diabetes mellitus mice receiving insulin treatment." (PMID 34803500, 2021). "The direct association between grip strength and type 2 diabetes could be explained by resistance training-induced improvements in glucose homeostasis, whereby resistance training lowers HbA1c levels and upregulates key proteins in the insulin signalling cascade." (PMID 32813182, 2021). "Puerarin (PUE) is a Chinese traditional medicine known to enhance glucose uptake into the insulin cells to downregulate the blood glucose levels in the treatment of type II diabetes." (PMID 33477727, 2021). "Exercise increases GLUT4 content and GLUT4 translocation to the plasma membrane in type 2 diabetes, thereby increasing glucose transport and insulin sensitivity." (PMID 33746668, 2021). "A total of 285 participants were included in this current study; 58.9% had type II diabetes and 41.1% had type I diabetes, and 71.9% of patients were on insulin injection treatment." (PMID 34603896, 2021). "The one patient commenced on insulin had type 2 diabetes prior to admission managed with oral therapy, and insulin was discontinued soon after discharge when they were readmitted with hypoglycaemia." (PMID 34268452, 2021). "Among these factors, insulin/IGF and ROS associated to metabolic disorders such as type II diabetes and obesity can be included." (PMID 35118400, 2021). "Overall, people with type 2 diabetes and hospitalization more often received insulin‐based regimens (either monotherapy or insulin combined with one glucose‐lowering drug) (55%) than did comparisons (45%)." (PMID 34277957, 2021). "There are many possible reasons for this low rate of solved insulin-related DRPs in diabetes type 2 patients." (PMID 34449695, 2021). "Strong international evidence shows that type 2 diabetes can be prevented by accurate management of the dysregulated blood glucose and insulin." (PMID 34490230, 2021). "The majority of oral hypoglycemic drugs, such as glibenclamide used to manage type 2 diabetes, work by stimulating the secretion of insulin by the pancreatic beta cells, hence leading to a rise in the serum insulin level following administration." (PMID 34912223, 2021).
type 2 diabetes (continued). "Regular exercise training has been shown to regulate the phosphorylation of TBC1 domain family member 4 (TBC1D4) in skeletal muscle from individuals with type 2 diabetes, indicating a role for RabGAP in the insulin-sensitising effects of exercise training." (PMID 33912980, 2021). "We aimed to investigate the effect of MR blockade on insulin sensitivity in individuals with type 2 diabetes compared to healthy controls, assessing insulin sensitivity by performance of a two‐stage hyperinsulinemic‐isoglycemic clamp." (PMID 34350730, 2021). "Exercise can prevent and treat type 2 diabetes arising from obesity by improving insulin sensitivity through increased glucose uptake in skeletal muscle." (PMID 34234788, 2021). "Reducing the circulation of fatty acids is an effective strategy to improve insulin sensitivity in type 2 diabetes." (PMID 33746668, 2021). "In order to recommend the optimal type of exercise for type 2 diabetes prevention, different exercise interventions were compared with respect to their effects on glycemic control and insulin resistance." (PMID 34488728, 2021). "We recruited a total of 160 type 2 diabetics, who received insulin (n = 40), liraglutide (n = 40), empagliflozin (n = 40), or their combination (GLP-1RA+SGLT-2i) (n = 40)." (PMID 34573011, 2021). "Genetically-determined, peripheral, insulin-related, signaling traits such as type 2 diabetes were found to be related to aggressive taboo thinking while genetically-determined, fasting, insulin levels and 2 h glucose levels were correlated with OCD." (PMID 34746045, 2021). "Type 2 diabetes (T2D) is a chronic degenerative inflammatory disorder characterized by insulin dysfunction and chronic hyperglycemia." (PMID 34944461, 2021). "Significant associations were also found in age, gender, type 2 diabetes, hypertension, serum creatinine, eGFR and the use of aspirin, ACEI/ARBs, insulin and metformin as well." (PMID 33419413, 2021). "In fact, comparing GLP-1 alone administration, the co-infusion resulted in similar blood glucose and insulin secretion rates in type 2 diabetes, but the suppression of plasma glucagon by GLP-1 was antagonized by GIP." (PMID 35054422, 2021). "Tests of differences by age, sex, racial/ethnic groups, and (for type 2 diabetes) insulin use found significant heterogeneity across all (P ≤ .01 for all)." (PMID 34468753, 2021). "Only 4% of patients had Type 2 Diabetes and were on insulin, while the other 96% had Type 1 Diabetes." (PMID 34020722, 2021). "Results of KEGG enrichment were similar, for example, “pancreatic secretion” (gene count = 24, p = 8.31E − 08), “insulin secretion” (gene count = 19, p = 5.11E − 06), and “type II diabetes mellitus” (gene count = 10, p = 0.001)." (PMID 33728329, 2021). "A cohort was constructed including women of age 20 to 44 years with type 2 diabetes in Taiwan that had an insulin group, a metformin group, and a group that switched from metformin to insulin." (PMID 34804675, 2021). "Individuals who developed either prediabetes or type 2 diabetes were older, with higher BMI, waist circumference, serum glucose, insulin and HOMA-IR, liver enzyme concentrations (ALT and GGT), TG concentrations and FLI values." (PMID 34309471, 2021). "In the case of people with type II diabetes, the pancreas produces insulin, but their body cannot use it effectively for decreasing blood sugar concentration." (PMID 34045956, 2021). "In one study, the prevalence of NAFLD was low in individuals with type 1 diabetes (8.8%) and in those with type 2 diabetes NAFLD prevalence was lower in insulin-treated (61.7%) than in insulin-naive (75.6%) individuals." (PMID 33877366, 2021). "In contrast to the normal glucose tolerant subjects, individuals with type 2 diabetes are characterized by overt elevated basal HGP despite high basal plasma insulin or C-peptide concentrations." (PMID 33498493, 2021).
type 2 diabetes (continued). "Sulfonylureas, insulin secretagogues, are the earliest and most widely used oral hypoglycemic drugs used for type-2 diabetes." (PMID 34539410, 2021). "The feature of insulin resistance in diabetes mellitus type II accounts for 90%–95% of the diabetic population which fails insulin function." (PMID 35223819, 2021). "Among patients with type 2 diabetes, 42,171 (63.8%) were treated with oral glucose-lowering drugs (OGLDs) alone, 7566 with insulin alone (11.4%) and 14,529 (22.0%) with OGLDs plus insulin." (PMID 33594476, 2021). "Type 2 diabetes patients are mainly treated with sulfonylureas, biguanides, alpha glucosidase inhibitors, insulin sensitizers, and glinide insulin secretagogues." (PMID 34367309, 2021). "Our findings indicate that AMGB has the potential to control TNF-alpha, mTOR, extracellular signal-regulated kinases (ERK), IRS, and PI3K, consequently improving the insulin signaling pathway and preventing type II diabetes mellitus." (PMID 34944525, 2021). "This review provides up-to-date information regarding the ER, ER stress mechanisms, insulin dysfunction, oxidative stress, and the therapeutic potential of targeting ER stress in type II diabetes." (PMID 34299638, 2021). "Many different oral antidiabetic drugs (OADs) combined with insulin have been approved for type 2 diabetes (T2DM), including metformin, incretin analogs, and sodium–glucose cotransporter (SGLT) 2 inhibitors (SGLT-2is)." (PMID 33651228, 2021). "Adults with type 1 diabetes showed slightly more optimal medication intake and fewer perceived barriers than adults with non-insulin treated type 2 diabetes." (PMID 36994341, 2021). "The increase in low intensity physical activity is encouraging as this has been shown to improve insulin sensitivity in people diagnosed with type 2 diabetes as per the study by Sardinha, Magalhães, Santos, and Júdice (2017)." (PMID 34770110, 2021). "Insulin glargine is a long-acting human insulin analogue that allows for once-daily basal use in patients with type 1 or type 2 diabetes." (PMID 34174848, 2021). "The procedure can be further complicated when considering medication such as insulin and oral hypoglycaemia medications such as those with type 2 diabetes." (PMID 35242045, 2021). "In a recent meta-analysis, it was determined that resistant starch supplementation improved insulin sensitivity and lowered blood glucose and fasting insulin levels in patients with type 2 diabetes and obesity." (PMID 34684471, 2021). "We aimed to compare cardiovascular outcomes of patients with type 2 diabetes (T2D) who initiated GLP-1 receptor agonists (GLP-1RA) or basal insulin (BI) under routine care." (PMID 34774054, 2021). "A 58-year-old type 2 diabetes female patient suffered a rapid and dramatic decline of vision acuity in the left eye in 2 months after the insulin IT." (PMID 33607771, 2021). "Previous studies have shown that OP consumption exerts therapeutic effects on the early stage of type 2 diabetes by repairing islet morphology, regulating insulin secretion, and improving glucose tolerance and insulin sensitivity." (PMID 34206641, 2021). "Although these patients are more likely to use insulin, optimal glucose regulation is generally more difficult than for those with type 2 diabetes." (PMID 34033299, 2021). "During both the low and high dose of infused insulin, plasma insulin levels rose to a high, but physiological plateau, compared to baseline during both clamps in both the individuals with type 2 diabetes and the healthy controls." (PMID 34350730, 2021). "The main pathophysiologic facts that lead to type 2 diabetes (T2D) are peripheral insulin resistance and final destruction of insulin producer pancreatic beta cells." (PMID 33807621, 2021). "What are the trends in ambulatory insulin use among adults with type 2 diabetes in the United States between 2016 and 2020?" (PMID 34636912, 2021).
type 2 diabetes (continued). "A total of 6582 adult patients (aged ≥18 years) with type 2 diabetes who were receiving insulin therapy were enrolled in the study." (PMID 33544081, 2021). "This situation is either characterized by insufficient secretion of insulin from β-cells of pancreatic islets (type 1 diabetes) or the inability of cells to react in response to the secreted insulin (type 2 diabetes)." (PMID 33916183, 2021). "The present study demonstrated that oral treatment with HBN exerted anti-diabetic effect and improved glucose tolerance in type 2 diabetic mice by protecting the pancreatic β-cells and improving insulin signaling in the liver and adipose tissue." (PMID 33986669, 2021). "In the incipient stage of type 2 diabetes, there is a transient compensatory rise in insulin secretion from pancreatic β cells to meet the increased metabolic demands as in patients with impaired glucose tolerance and ob/ob mice." (PMID 33980820, 2021). "The objective of this analysis was to determine the immunogenicity profiles in patients with type 1 diabetes and in patients with type 2 diabetes treated with MYL-1501D or reference insulin glargine." (PMID 34174848, 2021). "The results of these studies demonstrated that GLP-1R agonists and DPP-4 inhibitors significantly upregulate the insulin response and can improve hyperglycemia in patients with type 2 diabetes." (PMID 34205264, 2021). "In ECs from humans with advanced atherosclerosis and type 2 diabetes, we showed that at 100-nM insulin-induced Akt phosphorylation was preserved, whereas eNOS phosphorylation was blunted." (PMID 34420367, 2021). "IR is defined as a condition of low insulin sensitivity which leads to compensatory hyperinsulinemia, it plays a major role in the pathogenesis of type 2 diabetes and the development of complications." (PMID 34352018, 2021). "One of the common situations between early stage of type 2 diabetes and metabolic syndrome is hyperinsulinism with resistance to insulin." (PMID 35018210, 2021). "This study aimed to examine the effects of l-citrulline (l-CIT) on low-grade inflammation (meta-inflammation) and insulin sensitivity in type 2 diabetes (T2D) patients since it has exhibited hypoglycemic and anti-inflammatory effects in most animal studies." (PMID 33952324, 2021). "It has also been shown that insulin-independent glucose disposal is impaired in obesity and type 2 diabetes." (PMID 34168617, 2021). "The levels of glucose and insulin were significantly different which indicates type 2 diabetes in the study group." (PMID 34769939, 2021). "It is unclear which particular aspects of type 2 diabetes are responsible for the damaging effects on bone, as it is a complex disease characterised by both high blood glucose and complications with insulin action or secretion." (PMID 33650017, 2021). "LY2405319, another FGF21 analog, was found to improve lipid levels, lipoprotein profile, body weight, fasting insulin, and adiponectin levels in obese patients with type 2 diabetes in a randomized, placebo-controlled, double-blind clinical trial." (PMID 34513950, 2021). "The aim of this project was to investigate if 8 weeks of treatment with a MR antagonist, would improve insulin sensitivity in individuals with type 2 diabetes compared to healthy controls." (PMID 34350730, 2021). "Materials and methods: A sample of 100 participants with type 2 diabetes aged 40 and over was divided into case and control groups, according to their insulin requirement." (PMID 34577866, 2021). "Growing evidence supports the assumption that WISP-1 plays a role in the complex continuum, which consists of excessive body weight, impaired insulin sensitivity and finally, type 2 diabetes." (PMID 33498604, 2021). "Ci-Ins2 and its human ortholog ci-INS are downregulated in type 2 diabetes, predominantly localized in the nucleus, and interact with TARDBP." (PMID 34449657, 2021).